INS (insulin)
Diseases named in the same sentence as INS in open-access papers (continued):
Sharing a sentence is not in itself a finding about the gene and the disease.
diabetes (continued). "Glucose toxicity, inflammation, oxidative stress, insulin resistance, blood–brain barrier disruption, and cerebral macro- and microvascular disease associated with diabetes are the well-established pathophysiological mechanisms linking diabetes with cognitive impairment." (PMID 26753625, 2016). "However, we found little evidence that this group of patients might present an increased risk of developing insulin disturbances that may result in the future in diabetes or metabolic syndrome." (PMID 27212946, 2016). "Likewise, CIRKO mice represent a useful model to dissect the mechanisms and the effects of insulin in the heart, in the absence of systemic effects of insulin deficiency, or the additional conditions associated to systemic effects of insulin treatment as occur in many models of diabetes." (PMID 27014078, 2016). "In regards to the physiological role of insulin in the regulation of Kv channels and their association with cardiac electrical function specifically, this relationship would be given by an altered intracellular signaling in a similar way to the pathological processes involved in diabetes mellitus." (PMID 27014078, 2016). "Since self-association of insulin into large aggregates represents significant mechanical problems in insulin delivery devices and might cause complications during diabetes treatment, chemical modifications of this protein were elaborated to generate insulin analogues that can resist aggregation." (PMID 26983499, 2016). "Diabetes mellitus (DM) is a chronic metabolic disease defined by elevated glycemic markers, and is associated with disrupted insulin secretion, insulin resistance, and lipid metabolic disorder." (PMID 27669240, 2016). "Additionally, the loss of tissue-specific insulin signaling induced by hyperglycemia and toxic metabolites can induce cellular dysfunction and both macro- and microvascular complications characteristic of diabetes." (PMID 26881236, 2016). "Diabetes mellitus (DM) is a metabolic disorder characterized by chronic hyperglycemia, caused by the absence or reduction in insulin production (type 1 DM) as well as the resistance to the action of this hormone, featuring type 2 DM." (PMID 27999319, 2016). "Because changes in glucose concentrations, insulin sensitivity or insulin secretion can precede diagnosis of diabetes to up to 6 years, the increased risk of cancer could also predate clinical diagnosis of diabetes." (PMID 25916213, 2016). "Diabetes mellitus (DM) is the complication caused either by the poor tissue responsiveness to insulin or by the metabolic malfunction of insulin production." (PMID 27034931, 2016). "In addition, drugs used in diabetes, like insulin and analogues, were associated with dizziness but this may also be explained by the association between diabetes and dizziness." (PMID 27590725, 2016). "Moreover, a longer duration of diabetes is known to be associated with poor glycemic control, and this could be explained by progressive impairment of insulin secretion over time because of beta cell failure." (PMID 28090538, 2016). "The vast majority of diabetes cases fall into 2 major etiopathogenetic categories, Type 1 diabetes which occurs as a result of absolute deficiency of insulin secretion and Type 2 diabetes which is caused by a combination of insulin resistance and a faulty compensatory insulin secretory response." (PMID 26923830, 2016). "Diabetes mellitus (DM), especially type 2, demonstrate compromised insulin secretion associated with β cells dedifferentiation." (PMID 27486772, 2016). "Frank diabetes presents when β-cells are incapable of compensating for insulin resistance, and this is associated with some loss of β-cell mass, whose extent is debated (25–50%), compounded by impaired glucose-stimulated insulin secretion from the remaining β-cells." (PMID 28123396, 2016).
diabetes (continued). "NAFLD increases diabetes risk via mechanisms that increase the secretion of hepatokines such as fetuin-A, and plasminogen-activator inhibitor-1, increase gluconeogenesis, decrease glycogen synthesis, and inhibit insulin signaling; Metabolically at-risk is closely correlated with visceral adiposity." (PMID 26511621, 2015). "The in utero transmission of risk for diabetes from a mother to her offspring, whether genetic or environmental, potentially involves modulation of circulating cytokines that influence appetite regulation, insulin action, or other metabolic functions." (PMID 26111704, 2015). "Diabetes mellitus is a group of metabolic diseases associated with chronic hyperglycemia, which occurs as a consequence of destructive lesions of the pancreatic beta cells causing insufficient insulin secretion and several other etiological processes leading to decreased insulin sensitivity." (PMID 26430576, 2015). "Although the patients and healthy subjects in this study had not undergone genetic testing, increased body weight in such individuals with decreased insulin secretory ability may have increased insulin resistance and it may have increased their susceptibility to developing diabetes." (PMID 26215867, 2015). "Previous study showed that insulin therapy has a significant association with depression among adult patients with diabetes, however, insulin therapy wasn’t associated with the depression symptoms in this study, this may be related to the characteristics and the size of this sample." (PMID 26167205, 2015). "Besides insulin, new diabetes treatments could also influence cancer risk, although this notion is controversial." (PMID 25965806, 2015). "In summary, in a followup of a nationally representative cohort of female patients with diabetes, insulin use (mainly human insulin) for 3 years or more may be associated with breast cancer mortality, with a fully adjusted hazard ratio (95% confidence interval) of 2.006 (1.102–3.653)." (PMID 26171401, 2015). "The European regulations were also an attempt to individualize the risk associated with driving and allow some people with insulin-treated diabetes to drive Group 2 vehicles (large goods vehicles), provided they met strict criteria and could demonstrate safe driving practices." (PMID 28702227, 2015). "Indeed, a reduced risk of PCa is usually observed only several years after diabetes diagnosis, probably because long-standing diabetics may experience low insulin levels in later years." (PMID 26385727, 2015). "Diabetes mellitus (DM) belongs to a class of metabolic disorders, characterized by impairment of the insulin regulatory activity due to combined deficiency in hormone synthesis, secretion, and activity itself." (PMID 26347203, 2015). "Diabetes mellitus (DM) is a chronic disease accompanied by a series of metabolic disorders due to insulin deficiency or impaired insulin action." (PMID 26064877, 2015). "However, whether insulin use can be responsible for the increased risk of diabetes-related breast cancer is still under debate." (PMID 26537234, 2015). "However, the molecular mechanisms through which ADAMTS9 affects insulin sensitivity and/or secretion in the diabetes risk variant are unknown." (PMID 26218657, 2015). "Indeed, there is evidence that low glycemic index diets are effective in improving glucose metabolism and insulin sensitivity as well as various markers of cardiovascular risk in people with diabetes and obesity and can be considered in the overall strategy of diabetes management." (PMID 28702231, 2015). "As tight glycemic control is considered essential in limiting the risk of developing long-term complications of diabetes and taking into account the results obtained in this study Plantago ovata husk could have application in improving glucose and insulin control in people with type 2 diabetes." (PMID 26576433, 2015).
diabetes (continued). "Secondly, because insulin is not required it is plausible that harnessing these molecular mechanisms could represent an ideal avenue to improve both types of diabetes; the insulin-deficient type 1 (T1DM) and the insulin-resistant type 2 diabetes mellitus (T2DM)." (PMID 25870537, 2015). "Notably, previous analyses have suggested that later diabetes risk is influenced by a variety of risk factors including diagnostic glucose levels and ethnicity with more variable results between trials for family history, BMI and insulin use." (PMID 26844102, 2015). "For example, loss of insulin signaling in the pancreas could lead to diabetes." (PMID 28725688, 2015). "Furthermore, whether or not such increases in adiponectin would be associated with improved insulin sensitivity and decreased risk for diabetes is unknown." (PMID 26703682, 2015). "This is because high levels of physical activity aids the absorption of the hormone insulin into all the body’s cells, including the muscles, thus speeding up blood flow to the muscles and increasing energy consumption that translates to lower risk of diabetes by lowering blood glucose levels." (PMID 26714019, 2015). "Therefore, this study evaluated whether the use of insulin in a nationally representative cohort of female patients with diabetes in Taiwan increased the risk of mortality due to breast cancer, over a 12-year period of followup." (PMID 26171401, 2015). "DM results from either an absolute deficiency of insulin (type 1 diabetes, T1DM) or from insulin resistance with/without abnormal insulin secretion (type 2 diabetes, T2DM)." (PMID 26296196, 2015). "Diabetes mellitus (DM) is a metabolic disease associated with disrupted insulin secretion or/and insulin action, resulting in high blood glucose levels." (PMID 26213526, 2015). "In addition, impaired insulin signalling found in diabetes could also affect this process causing a derangement of glucose metabolism which can impact on neuronal development, learning and memory." (PMID 26193295, 2015). "Diabetes mellitus (DM) is a chronic metabolic disorder caused by impairment of insulin production by pancreatic β cells and/or defects in insulin action." (PMID 26308046, 2015). "Other preoperative patient factors have been associated with the outcomes of diabetes remission, including age, fasting C-peptide concentration, BMI, glycemic control (A1c), and medications used to manage blood glucose, including oral hypoglycemic agents and insulin." (PMID 25954762, 2015). "Induction of diabetes with alloxan was also associated with decrease in hepatic glycogen, which could be attributed to the decrease in the availability of the active form of enzyme glycogen synthetase, probably because of low levels of insulin." (PMID 25695047, 2015). "Diabetes mellitus (DM) is a metabolic disorder caused by absolute insulin deficiency or insufficient insulin secretion and/or insulin sensitivity and is characterized by hyperglycemia." (PMID 26221612, 2015). "However, whether the use of exogenous insulin (i.e., human insulin or insulin analogues) for treating hyperglycemia in patients with diabetes actually increases the risk of breast cancer is the subject of recent debate." (PMID 26171401, 2015). "Similarly, since PSMD9 is a coactivator of insulin gene transcription, and in pancreatic overexpression of transgenic mice cause diabetes, PSMD9 variants may contribute to T2DM as well as to obesity." (PMID 25928419, 2015). "It is therefore reasonable to speculate that reduced expression of key ZIPs, including ZIP6 and ZIP7, may disrupt zinc homeostasis and produce subsequent defects in insulin secretion and reduce β cell viability, potentially increasing the risk of developing diabetes." (PMID 25969539, 2015).
diabetes (continued). "Additionally, Ibrahim reported that abdominal obesity imparts a greater risk of developing diabetes and future cardiovascular events than peripheral or gluteofemoral obesity, and visceral adipose tissue has a higher rate of insulin-stimulated glucose uptake compared with subcutaneous obesity." (PMID 26273678, 2015). "Diabetes, characterized by persistent elevation of blood glucose levels (hyperglycaemia), occurs due to inadequate production of insulin (type 1 diabetes) or resistance to endogenous insulin usually associated with metabolic syndrome and obesity (type 2 diabetes)." (PMID 24719887, 2014). "Diabetes mellitus (DM) is a disease caused by a deficiency or diminished effectiveness of endogenous insulin." (PMID 25072200, 2014). "Although this diabetes-reversal effect of Imatinib has been suggested to be associated with its anti-inflammatory effect as well as improving insulin sensitivity, whether Imatinib has direct effects on β cells to promote insulin production is yet to be addressed." (PMID 24835010, 2014). "Diabetes mellitus (DM) is a chronic disease characterized by hyperglycemia resulting in insulin resistance and/or insulin secondary deficiency caused by the failure of beta- (β-) pancreatic cells." (PMID 24977161, 2014). "Diabetes Mellitus (DM) is a metabolic syndrome resulting from the production, secretionor deficient use of insulin characterized by chronic hyperglycemia, frequentlyaccompanied by dyslipidemia, abnormal blood pressure and endothelial dysfunction." (PMID 25591093, 2014). "The NSY mouse shares many features of diabetes with human type 2 diabetes in that the onset is age-dependent, the disease is associated with moderate obesity with abdominal fat accumulation, and both impaired insulin response to glucose and insulin resistance contribute to the disease development." (PMID 25167881, 2014). "Type II diabetes, otherwise known as Diabetes Mellitus (DM), is a condition that occurs when a person becomes insensitive towards insulin causing an increase in bloodstream glucose levels (hyperglycemia)." (PMID 24718615, 2014). "Reductions in both 6-month fasting insulin and HOMA-IR with metformin, and in HOMA-IR with combination therapy, suggest that insulin sensitizing medications may confer additional benefit beyond weight loss, in populations with documented insulin elevation and presumed diabetes risk." (PMID 25259787, 2014). "Diabetes mellitus is a dysfunction of the glucose metabolism caused by an absence or insufficient production of insulin and it is classified into type 1 with autoimmune destruction of insulin-secreting β cells, and type 2: metabolic disorders which comprise 95% of diabetes mellitus cases." (PMID 24835775, 2014). "Moreover, dietary composition could play a significant role in improving insulin sensitivity and reducing risk of diabetes and its complications." (PMID 25551102, 2014). "However, in all these clinical studies it is very difficult to separate the systemic effects of inflammation or hyperglycemia-associated sepsis, which may occur during diabetes, from the loss of any direct protective effects of insulin within the pancreas." (PMID 24993827, 2014). "β-cell dysfunction with progressive loss of pancreatic β-cell insulin secretion, subsequent to the development of insulin resistance, are key defects associated with the transition from a healthy glycemic state to hyperglycemia, characteristic of untreated type 2 diabetes mellitus (T2DM)." (PMID 24524730, 2014). "One such disorder is diabetes mellitus (DM) which is a chronic disease characterised by prolonged hyperglycaemia, especially post-prandial, in association with the consumption of diets that promote obesity, due to abnormalities in plasma insulin concentrations." (PMID 25070239, 2014).
diabetes (continued). "Other controversial factors included diabetes managed by insulin administration, which some researchers have indicated as a risk factor for sternal wound infection In the present study, preoperative insulin use was significantly higher in the group of patients with sternal wound infection." (PMID 24885820, 2014). "Research has also illustrated the contribution that altered circadian rhythm and sleep patterns might result in disrupted metabolic functioning, including impaired insulin sensitivity and increased risk of diabetes, obesity and cardiovascular events in the general population." (PMID 24742112, 2014). "The associations of BMI with beta cell function, and insulin sensitivity with smoking status should be explored further as these are important risk factors that may be modified as a means of preventing the progression to full diabetes." (PMID 24416185, 2014). "Diabetes mellitus (DM), characterized by chronic hyperglycemia resulting from deficiency of insulin secretion, resistance to insulin action or both, is associated with long-term damage, dysfunction and failure of various organs." (PMID 25104050, 2014). "Diabetes mellitus (DM) is a chronic disorder of glucose metabolism caused by impaired secretion of insulin from pancreatic β-cells, which affects the central and peripheral nervous systems." (PMID 25050332, 2014). "Interestingly, a mouse model of marked peripheral insulin resistance was characterised by an age-related development of diabetes that was linked to a decrease in both pancreatic beta cell mtDNA content and mitochondrial function, and decreased glucose-stimulated insulin secretion." (PMID 25532126, 2014). "Given the protective effect of high total serum bilirubin levels in preventing diabetes, focus of the present study will be to examine the association between accelerometer-assessed physical activity and total serum bilirubin levels among insulin sensitive and insulin resistant adults." (PMID 24708607, 2014). "Both amount of deep subcutaneous and visceral adipose tissue correlates with an increased risk of diabetes, while subcutaneous fat in the gluteofemoral region and the superficial depot has been shown to be more beneficial and associated with improved insulin sensitivity and reduced risk of diabetes." (PMID 25148116, 2014). "Moreover, models of insulin-deficient diabetes result in increased GLUT4 phosphorylation, which may render GLUT4 less sensitive to acute regulation by insulin." (PMID 24624139, 2014). "Diabetes mellitus (DM) is a chronic disease caused by inherited or acquired deficiency in insulin secretion and by decreased sensitivity of the organs to secreted insulin." (PMID 25324703, 2014). "Because elevated postprandial levels of TG and glucose represent metabolically abnormal responses that reflect insulin resistance, higher risks of diabetes or cardiovascular events might be associated with a higher postprandial TyG index, which remains to be clarified." (PMID 24587359, 2014). "The American diabetes association and the European association for the study of diabetes guidelines recommend lifestyle modification first and then propose the addition of basal insulin, sulfonylurea and thiazolidinediones if HbA1c still exceeds in the initial stages of DN." (PMID 28197454, 2014). "Accordingly, this study evaluated the effects of insulin treatment on the outcome of islet transplantation in Akita mice, which carry an Insulin 2 (Ins 2) gene missense mutation and exhibit insulin deficiency, thus making them an excellent model for diabetes with long-term sustained hyperglycemia." (PMID 24743240, 2014). "Diabetes has been established as an independent risk factor for lung cancer.Increasing evidence has shown that conventional glucose-lowering drugs such as insulin, insulin sensitisers and secretagogues, may influence the risk of cancer." (PMID 24924771, 2014).